INS (insulin)
Diseases named in the same sentence as INS in open-access papers (continued):
Sharing a sentence is not in itself a finding about the gene and the disease.
Obesity (continued). "It is important to recognize T1.5DM a distinct subtype of DM in children that is characterized by the co-existence of the etiologic processes of autoimmunity and the peripheral defects in insulin signaling in the same patient, factors that are primarily due to obesity (IR)." (PMID 27992493, 2016). "This diet has been employed as an obesity induction model in rats and mice and has been accompanied by increased body weight, adiposity, levels of leptin, and plasma concentrations of cholesterol, glucose, and insulin." (PMID 28018521, 2016). "We hypothesised that beta cells expand in response to extreme obesity to meet the increasing insulin demand." (PMID 27003683, 2016). "Thus, accurate biomarkers or parameters reflecting insulin resistant state and metabolic risks are essential to understand its mechanism and to prevent obesity-related complications." (PMID 27642608, 2016). "This study design gives the opportunity to analyze the effect of transient pHA-induced obesity (P21) on metabolic programming of lung function in adulthood (P70) by evaluating adipose tissue-originated proinflammatory cytokines, insulin signaling and extracellular matrix (ECM) proteins in the lung." (PMID 27087690, 2016). "Therefore, we postulated that the improved glucose/insulin sensitivity and resistance to diet-induced obesity in FoxO1 KODAT mice were due, at least in part, to decreased food intake." (PMID 27681312, 2016). "In mice, administration of resistin impairs glucose tolerance and insulin action, implying that elevated levels of resistin may link obesity to diabetes." (PMID 27148161, 2016). "A duration of 90 days after SAT transplant into the omental and retroperitoneal intraabdominal compartments in the HFD‐ or HCHD‐induced obesity models, insulin sensitivity was improved, hepatic lipid content was reduced, and FFAs concentrations were also decreased." (PMID 27582062, 2016). "A similar phenotype has been reported using genetic animal models of obesity (db/db and ob/ob) in which insulin resistance settles at the early onset of the obese phenotype (5–10 weeks after weaning) while left ventricular hypertrophy is only apparent much later." (PMID 27832814, 2016). "It must be considered that multiple factors interact to control IGF-1 levels, many of which are disturbed in T2D, namely: increased inflammatory cytokines, decreased hepatic insulin action due to resistance, concomitant changes in IGFBPs, and the effects of obesity." (PMID 26733412, 2016). "Interestingly, the obese flies induced by Taotie neuron activation also display impaired insulin-related signals and increased expression of cytokines, further suggesting conserved mechanisms of obesity-related metabolic disorders across species." (PMID 27924813, 2016). "Impaired vasodilation to insulin has however been demonstrated in other tissues in obesity, and may be consistent with the presence of microvascular dysfunction." (PMID 27651131, 2016). "We found that hyperinsulinemia may be more prominent than hyperglycemia in the early stages of obesity-related metabolic disease, and elevated insulin may be a dominant sign of metabolic disease." (PMID 27069678, 2016). "Next, we tested whether inhibition of Gbb signaling would rescue HFD-induced obesity and the insulin-resistant phenotype." (PMID 27484164, 2016). "Differences in prevalence and degree of obesity, fat partition, genetic background, and insulin sensitivity may contribute to explain the observed discrepancies." (PMID 27559364, 2016). "Indeed, it has been described that excessive glucose uptake and obesity result in both insulin pathway‐dependent and pathway‐independent mTORC1 and S6K1 activity." (PMID 27613445, 2016). "However, insulin resistance likely represents a physiological feedback mechanism to actually retard the development of obesity‐driven complications." (PMID 27137487, 2016).
Obesity (continued). "Altogether, these experimental observations suggest that S263 phosphorylation of ACSS2 plays a crucial role in maintaining triglyceride level and in modulating insulin-induced AKT phosphorylation during obesity, thus highlighting it as a potential target in regulating glucose and lipid homeostasis." (PMID 27180971, 2016). "This in turn corrects glucose and insulin levels in obesity and restores glucose homeostasis." (PMID 27430475, 2016). "Notably, when fed a high-fat diet (HFD), Pla2g5−/− mice display hyperlipidemia with higher plasma levels of LDL, increased obesity and hepatic steatosis, and lower insulin sensitivity." (PMID 29259680, 2016). "Our study does not only demonstrate that early-onset obesity transiently activates pulmonary adipocytokine/insulin signaling and induces airway hyperreactivity in mice, but also provides new insights into metabolic programming of childhood obesity-related asthma." (PMID 27087690, 2016). "Concomitant with the developing of HFD-induced obesity, a distinct insulin-resistance was obtained." (PMID 27028201, 2016). "Understanding the role of REDD1 in insulin action and energy homeostasis may provide a roadmap toward designing strategies to counteract obesity-related metabolic disorders." (PMID 27613400, 2016). "Interestingly, several of the prioritised genes are known to have a role in insulin secretion, insulin sensitivity or obesity." (PMID 29263820, 2016). "Because adipose TNMD expression improves insulin sensitivity systemically, it may have potential as a therapeutic target to protect metabolic homeostasis in obesity." (PMID 26880110, 2016). "Furthermore the insulin resistant state of obesity is characterised by increased plasma levels of free fatty acids that have cardiotoxic effects and impair the production of endothelial vasodilators." (PMID 26956847, 2016). "For example, obesity may affect brain structure, leptin and insulin dysregulation, oxidative stress, cerebrovascular function, blood-brain barrier, and inflammation." (PMID 26881095, 2016). "Furthermore, very few participants born in Iraq with obesity or abdominal obesity (<5%) were insulin sensitive, indicating a low eligible proportion of participants with metabolic healthy obesity (MHO)." (PMID 27938404, 2016). "Other contributors often associated with obesity-induced carcinogenesis, including glucose and insulin, were not altered by diet exposures." (PMID 27042159, 2016). "Given the protective role of Oxt signaling, deficiency of Oxtr might impair cellular homeostasis as well as insulin-mediated glucose metabolism in pancreatic islets, which will collectively lead to late-onset obesity." (PMID 27143105, 2016). "Therefore, obesity performs a complex biological activity regulation like cytokines production leading insulin resistance or deregulation of IGF1 and immune system among others." (PMID 26801617, 2016). "Substantial research has shown that obesity affects our cognition and motor behaviors through different mechanisms, possibly through altering brain structure, leptin/insulin regulation, oxidative stress, cerebrovascular function, blood-brain barrier, and inflammation." (PMID 26881095, 2016). "Moreover, the associations between various conditions (e.g., colic, laminitis, and obesity/insulin dysregulation) and characteristic shifts in the composition of the equine GM need to be reproduced and examined for causality." (PMID 27846295, 2016). "Additionally, adiponectin, the insulin-sensitizing adipokine found at low circulating levels in obesity that has been observed to increase GLUT4 expression, was found at lower levels in 3-AT treated cells." (PMID 27023799, 2016). "Obesity is often accompanied by disorders of glucose and insulin homeostasis." (PMID 27190511, 2016). "It shows that obesity is an important factor for the indication of insulin therapy." (PMID 27478440, 2016).
Obesity (continued). "As highlighted in this work by in vivo and ex vivo measurements of insulin sensitivity, skeletal muscle IR is an early event in obesity-related IR pathogenesis, which develops before any detectable macrophage infiltration in tissues, any SAT defect in insulin signaling or any systemic inflammation." (PMID 27111539, 2016). "It was proved in several clinic researches that chronic sleep disturbance are related to obesity and hyperlipemia, which may reduce the insulin sensitivity." (PMID 27738407, 2016). "An additional parallel with Sirt1 is seen in our tissue-specific studies, where we show that sir2 function is necessary and sufficient in the fat body to maintain insulin signaling and suppress hyperglycemia and obesity, analogous to the role of Sirt1 in the liver and white adipose." (PMID 27058248, 2016). "Therefore, we examined relationships between adipokines, a marker of insulin production, and plasma FA desaturase enzyme activity estimates (EAEs) in obesity." (PMID 27023786, 2016). "Finally, adiponectin, a cytokine associated with anti-inflammatory processes, has been found to be increased on normal weight individuals and decreased on obesity; it also promotes fatty acid oxidation, increases insulin sensitivity and energy expenditure." (PMID 27527189, 2016). "In addition, knockdown of autophagy genes Atg5 and Atg7 in adipocytes can improve insulin sensitivity and relieve obesity." (PMID 27843198, 2016). "Obesity is considered a chronic, low-grade inflammatory condition and the adipose tissue is an active endocrine organ that has a key role in lipid and glucose metabolism, inflammation and coagulation, and insulin-mediated processes." (PMID 27455297, 2016). "Impaired insulin action promotes excessive fat accumulation, that is to say, obesity." (PMID 28025491, 2016). "Secondly, we aimed to investigate if resistance training affects femoral bone marrow (FBM) and VBM insulin sensitivity in these offspring and whether this outcome is regulated by their mother’s obesity status." (PMID 27669153, 2016). "Some studies suggest that augmented lactate levels in obesity, which might play a significant role in glucose transport and metabolism, profoundly influence insulin sensitivity." (PMID 28077918, 2016). "The high dietary intake of saturated fatty acids (SFA), which is the leading cause of obesity, frequently causes ectopic lipid accumulation and increase the risk of insulin resistance in non-adipose tissues, such as the liver and skeletal muscle." (PMID 27900351, 2016). "Our current observation of a higher proportion of M1/M2 macrophages in the adipose tissue of Atg7KO mice also suggests that autophagy in macrophages is important for regulating systemic insulin sensitivity and glucose tolerance by regulating the M1/M2 proportion in obesity." (PMID 27229537, 2016). "We did not evaluate a variety of other hormones known to link obesity to gonadotropin secretion, such as insulin, SHBG, and testosterone; as a result, we cannot prove causality." (PMID 27215137, 2016). "A six month RCT in children with obesity comparing a lower-GI (GI: 60) versus higher-GI (GI: 90) hypocaloric diet found that waist circumference, BMI z score, and insulin resistance were significantly reduced in the lower-GI compared with the higher-GI diet group." (PMID 27517953, 2016). "In addition, it worsens the deleterious effects of obesity on β cells, compromising the efficacy of therapeutic approaches to reestablish the triggering mechanisms of insulin secretion." (PMID 27633083, 2016). "Since protein intake or BCAA supplement will not influence plasma BCAA level too much, we highly recommend measurement of BCAA levels in order to capture the whole course of disease progress, including obesity, insulin resistant state, T2DM, and later drug effect." (PMID 27642608, 2016).
Obesity (continued). "Obesity could potentially alter the levels of multiple hormones and growth factors (e.g., testosterone, estrogen, leptin, insulin, and IGF-1) with competing effects on prostate growth and size." (PMID 27409334, 2016). "A high abundance of bifidobacteria could be protective in obesity since it is speculated that this bacteria may decrease pro-inflammatory cytokines and decrease endotoxaemia which can improve glucose-induced insulin and glucose tolerance." (PMID 27410967, 2016). "Thus, reducing circulating insulin with diazoxide or through partial ablation of the pancreas-specific Ins1 gene protects from high-fat diet (HFD)-induced obesity and its associated complications." (PMID 27677764, 2016). "However, in insulin-resistant states (obesity, prediabetes, and T2D), hepatic production of glucose and lipid synthesis are heightened in concert, implying that insulin deficiency and insulin excess coexists in this setting." (PMID 27291303, 2016). "High insulin-IGF blood concentrations in early infancy, as a result of infant formula composition e.g. higher protein content, increase BMI by 0.51 (0.13,0.90; p = 0.009) at school age and increase the risk for obesity." (PMID 26987056, 2016). "The comparison of induced obesity studies and spontaneous obesity studies can be misleading, because in spontaneous obesity it is not possible to accurately determine the time of fat mass accumulation and it can determine the development of insulin resistance." (PMID 28058131, 2016). "Exogenous stimulation of insulin release and resultant hypoglycemic episodes could be a reasonable mechanism by which obesity occurs in these adolescents." (PMID 27069678, 2016). "The increase in the activity levels of desaturase enzymes in obesity could be related to hyperinsulinemia arising from excess states, as insulin is a potent activator and regulator of delta-6 and delta-9 desaturases." (PMID 26891317, 2016). "Elevations of leptin and insulin contribute to obesity in rodent models." (PMID 27028862, 2016). "Given the complexities of these endocrine disturbances, it is difficult to determine causality particularly when likely candidates for altering vascular function such as insulin resistance, hyperinsulinaemia, cortisol dysregulation, inflammation and obesity often occur simultaneously." (PMID 27684374, 2016). "Finally, obesity is often related to high plasma insulin levels, a fact which contributes to the overproduction of sex hormones—estrogens and androgens—responsible for increased osteblast activity and reduced osteoclast activity." (PMID 27809297, 2016). "Findings from our study suggested that reduced p-Akt ser473 in PBMCs could reflect an impaired insulin stimulation status in obesity." (PMID 27481183, 2016). "The key determinant of “metabolic health” in obesity is insulin sensitivity." (PMID 26916476, 2016). "Our current analysis of saliva samples from 8,245 Kuwaiti 10-year-old adolescents suggests that obesity in this population is significantly associated with high salivary insulin concentration but not with high salivary glucose concentration." (PMID 27069678, 2016). "We initially speculated that the inverse relationship with C-peptide and D5D EAEs was likely due to underlying obesity-associated inflammation, since inflammation (i.e. TNF-α) alters insulin downstream signaling." (PMID 27023786, 2016). "Therefore, modulating mitochondrial function and efficiency in the skeletal muscle, they lessen pro-inflammatory, pro-oxidant signs and insulin resistance also in condition of nutritionally-induced obesity." (PMID 26901315, 2016). "In insulin resistant subjects, such as those with obesity and T2DM, a chronically high level of amino acids could maintain the hyperactivation of mTOR/S6K1, which works together to establish a negative feedback loop." (PMID 27376324, 2016).
Obesity (continued). "In conclusion, these findings suggest that cAMP signals generated by Adcy3 in peripheral tissues may play a pivotal role in modulating obesity and insulin sensitivity." (PMID 27678003, 2016). "Weight gain is an indicator of sustained positive energy balance and, along with adult obesity, affects circulating hormones, growth factors, insulin, and inflammatory cytokines which together can increase carcinogenesis, decrease apoptosis, and stimulate low-grade chronic inflammatory responses." (PMID 28003027, 2016). "Indeed, increased acetate production by gut bacteria has been found recently to promote insulin secretion, hyperphagia, and obesity, although there is also evidence that acetate is able to decrease appetite." (PMID 27900260, 2016). "Notably, the T2D GRS contributed to lower obesity-related measurements and greater β-cell dysfunction, including lower insulin levels in oral glucose tolerance test, decreased insulinogenic index, and Homeostasis Model Assessment for β-cell Function." (PMID 27281091, 2016). "In the converse genetic manipulation, reduced Ins2 dosage (on an Ins1-null background) led to high-fat fed female Ins1-/-:Ins2+/- mice having lower insulin secretion than their Ins1-/-:Ins2+/+ controls at a young age, which again corresponded with attenuated obesity." (PMID 27055260, 2016). "Expanding on a previous study that showed that excess dietary sugar increases fat accumulation in adult flies, Drosophila larvae fed a diet high in sucrose exhibited important aspects of obesity-related metabolic disorders, including fat accumulation, insulin resistance and hyperglycemia." (PMID 27604692, 2016). "First, Apoe−/− mice show obesity-resistant phenotype, resulting in remarkable insulin sensitivity." (PMID 26881239, 2016). "Interestingly, insulin secretion from adipocytes was recently reported suggesting a crosstalk between adipose tissue and pancreas in the regulation of energy metabolism in obesity and development of T2D3." (PMID 27356471, 2016). "Secondly we studied if a four-month individualized resistance training intervention increases bone marrow insulin sensitivity in elderly female offspring and whether this possible positive outcome is regulated by the offspring’s mother’s obesity status." (PMID 27669153, 2016). "In addition, C16:0 and C18:0 ceramides have been mechanistically linked to systemic metabolic health in genetic models and with insulin resistance in the muscle in obesity." (PMID 27135629, 2016). "Consequently, inhibiting of PTP1B was considered to be a potential therapeutics for treating Type 2 diabetes and obesity by enhance insulin sensitivity and resistance to obesity." (PMID 27999292, 2016). "Obesity reduced glucose tolerance and insulin sensitivity in normal- and low-protein-fed groups." (PMID 27633083, 2016). "Longitudinal studies are required to establish whether insulin sensitivity in obesity is sustained over time and whether it can be explained by unique tissue lipid signatures in humans." (PMID 26916476, 2016). "Interestingly, in our study, all patients with T1.5DM exhibited residual pancreatic β-cell reserves, implying that these patients exhibit a greater β-cell response then previously presumed, perhaps due to the insulin requirements secondary to obesity and IR." (PMID 27992493, 2016). "Helminths consume blood lipids and glucose, alter lipid metabolism, and modulate immune function towards Th-2 polarization—which combined can lower blood cholesterol, reduce obesity, increase insulin sensitivity, decrease atheroma progression, and reduce likelihood of atherosclerotic plaque rupture." (PMID 27666719, 2016). "sALCAM might be a novel biomarker in obesity that correlates and predicts insulin sensitivity improvement and that can be affected by lifestyle intervention." (PMID 27737658, 2016).